PLK1 (polo like kinase 1)
Diseases named in the same sentence as PLK1 in open-access papers (continued):
Sharing a sentence is not in itself a finding about the gene and the disease.
breast carcinoma (continued). "We then observed that most PLK1 signaling pathway-related genes were aberrantly upregulated in breast cancer, and that high expression of most of these genes closely correlated with a poor prognosis." (PMID 33902008, 2021). "Through the integration of network pharmacology-related databases and breast cancer target genes, we found that PLK1 is not only the target gene of breast cancer but also the target gene of podophyllotoxin." (PMID 32848800, 2020). "Our previously reported data show that TCTP is a direct substrate of PLK1 in mammary carcinoma cells." (PMID 32438775, 2020). "In accordance with previously reported data, demonstrating TCTP’s role as a key mitotic target of Plk1 in regulating anaphase progression we recently, showed that TCTP is a direct substrate of PLK1 in mammary carcinoma cell lines." (PMID 32438775, 2020). "Subsequently, the prognostic value of PLK1 in breast cancer was studied by Kaplan‐Meier plotter database, and it was confirmed that high expression of PLK1 mRNA was significantly associated with the decrease of RFS, OS, DMFS and PPS in breast cancer." (PMID 31837068, 2020). "Another similar formulation was developed by Sheng Yu and colleagues, showing synergistic activity of PDX and Polo-like kinase 1 (PLK-1)-targeting siRNA in limiting the progression of breast cancer." (PMID 32532030, 2020). "Reducing BRCA2 binding to PLK1, as observed in BRCA2 breast cancer variants S206C and T207A, alters the tetrameric complex resulting in unstable kinetochore-microtubule interactions, misaligned chromosomes, faulty chromosome segregation and aneuploidy." (PMID 32286328, 2020). "Plk1 mediates estrogen receptor (ER) which regulates gene overexpression in human breast cancer cells." (PMID 33247393, 2020). "Previous researchers have demonstrated that overexpression of PLK1 is closely related to lymph node metastasis of gastric cancer, lung squamous cell carcinoma and breast cancer." (PMID 33354424, 2020). "Through the comprehensive analysis of the databases, we found that the expression of CDC20, CDK1, and PLK1 are increased in breast cancer." (PMID 32848800, 2020). "In summary, we have confirmed the up‐regulation of PKMYT1 and its partner, PLK1, in breast cancer and validated their importance as prognostic factors." (PMID 31837068, 2020). "Our study reflects that CDK1, PLK1, and CDC20 are potential therapeutic targets of podophyllotoxin in breast cancer; among them, PLK1 is more worthy of further exploration." (PMID 32848800, 2020). "Together, these results show that VUS T207A and S206C identified in breast cancer patients impair phosphorylation of BRCA21–250 by PLK1 in vitro." (PMID 32286328, 2020). "We examined the effect of PLK1 inhibition via treatment with onvansertib, an oral available PLK1 inhibitor, alone or in combination with paclitaxel on mouse xenograft models of the mesenchymal breast cancer SUM159." (PMID 31751384, 2019). "Of note, these breast cancer samples with higher Plk1 levels have better clinical prognosis according to the genome-doubling feature." (PMID 30862113, 2019). "In this trend, and despite classical studies showing that Plk1 expression confers poor outcomes in breast cancer patients, there are reports showing the beneficial effects of Plk1 activity in breast cancer." (PMID 30862113, 2019). "In 2013, Plk1 was again proposed as a tumor suppressor in an elegant transcriptomic study done in human breast cancer cells by M. Beato and colleagues." (PMID 30862113, 2019). "mRNA expression, reverse phase protein array and immunohistochemistry showed a higher expression of Plk1 in TNBC compared with other subtypes of breast cancer and healthy breast tissue." (PMID 31751384, 2019). "Regarding the roles of the gene hits in cancer, PLK1 is overexpressed in numerous types of cancer, including lung cancer, breast cancer, hepatocellular carcinoma, head and neck cancer, cholangiocarcinoma, and uterine corpus endometrial carcinoma." (PMID 31387297, 2019).
breast carcinoma (continued). "The potential role of Plk1 as a tumor suppressor in breast cancer has been recently validated using knock-in mouse models, in the M. Malumbres’ and R. Sotillo’s laboratories." (PMID 30862113, 2019). "We have already investigated the interaction of ASCs with breast cancer cells, the effect of Polo-like kinase 1 (Plk1) inhibitors on ASCs, and the influence of obesity on ASCs." (PMID 31640218, 2019). "For example, analyzing the Cancer Genome Atlas (TGCA) database, we can observe that breast cancer samples that harbor genome doublings have a significant increase in Plk1 gene expression when compared to breast cancer samples that have a single genome copy." (PMID 30862113, 2019). "In a genome-scale short hairpin RNA (shRNA) screen of breast cancer cells, polo-like kinase 1 (Plk1) was a frequent and strong hit in the basal breast cancer cell lines indicating its importance for growth and survival of these breast cancer cells." (PMID 31751384, 2019). "In patients, Plk1 overexpression correlates with improved survival in specific breast cancer subtypes." (PMID 30069007, 2018). "Our analysis of human breast cancer datasets shows that tumors with higher PLK1 expression generally have improved prognosis." (PMID 30069007, 2018). "This strategy, aimed at targeting the delivery of PLK1 siRNA to breast cancer, resulted in specific PLK1 knockdown in vitro and in human ex vivo cultured cells." (PMID 30340426, 2018). "Next, to explore the relationship between PLK1 expression and ploidy in human breast cancers, we obtained matched copy number and expression data for 953 breast tumors from the TCGA." (PMID 30069007, 2018). "In breast cancer, subnetwork modules encompassing proliferation pathways (Mitosis, PLK1, AURKA, and AURKB) were highly prognostic." (PMID 30420699, 2018). "We found that inhibition of two well studied oncogenic pathways (MEK1/2 and PLK1 axes) in breast cancer significantly reduced outgrowth of basal‐like syngeneic and human breast tumors xenografts in preclinical models." (PMID 30108112, 2018). "Our data relate to recent findings about PLK1 in breast cancer cells showing that PLK1 modulates estrogen-dependent transcription of genes that have important tumor suppressive functions." (PMID 29549256, 2018). "Dual inhibition of MAPK signaling (MEK1/2 inhibition) and the mitotic pathway (PLK1 inhibition) synergistically reduced the outgrowth of both murine and human breast cancer cells." (PMID 30108112, 2018). "Contrary to these examples, Plk1 overexpression results in a significant delay and decreased breast cancer incidence in combination with Kras and Her2 oncogenes." (PMID 30069007, 2018). "Combining inhibitors of MEK1/2 (targets the MYC‐CEP55 axis) and PLK1 (mitosis) inhibited the outgrowth of aggressive basal‐like syngeneic and human breast cancer xenografts." (PMID 30108112, 2018). "Plk1 overexpression also prevents malignant transformation of primary cells by Ras oncogenes and impairs breast cancer development induced by Kras or Her2 oncogenes." (PMID 30069007, 2018). "A meta-analysis of breast cancer patients suggests that PLK1 overexpression at the mRNA level correlates with poor prognosis in ER+." (PMID 30069007, 2018). "In human breast cancer cells, Plk1 mediates estrogen receptor (ER)-regulated gene transcription participating in the expression of genes involved in developmental and tumor-suppressive functions." (PMID 30069007, 2018). "PLK1 inhibition by a small molecule inhibitor hindered brain metastases and prolonged survival in a mouse model of breast cancer brain metastasis." (PMID 28953239, 2017). "PLK1 phosphorylates vimentin on S82, which regulates cell surface levels of β1 integrin and thereby promotes the invasiveness of breast cancer cells." (PMID 28953239, 2017).
breast carcinoma (continued). "Among those five E2F targets correlated with malignant transition, Cdk1 and Plk1 were well studied in breast cancer, but much less so for Ccnb2, Aurkb, and Spag5 (7, 10, and 3 reports, respectively)." (PMID 28212608, 2017). "Diagnostic biopsies of breast cancer patients were analyzed by immunohistochemistry for the expression of FBXW7, MCL1 and PLK1." (PMID 27409838, 2016). "In summary, we show that FBXW7 plays a prominent role in paclitaxel-induced apoptosis by regulating MCL1 and PLK1 levels in breast cancer, as resistant cells loose FBXW7 and accumulate these substrates." (PMID 27409838, 2016). "We also show that breast cancer cell lines with high mitotic activity are preferentially sensitive to small molecule inhibitors that target mitotic apparatus proteins PLK1, CENPE and AURKB/C, designated GSK462364, GSK923295, and GSK1070916, respectively." (PMID 27368372, 2016). "This prompted us to consider FBXW7 as an important mediator of the paclitaxel response through the control of MCL1 and PLK1 degradation in breast cancer." (PMID 27409838, 2016). "In breast cancer tissues, loss of FBXW7 correlated with adverse prognosis markers and loss of FBXW7 and MCL1 or PLK1 accumulation were associated with diminished disease-free survival in paclitaxel-treated patients." (PMID 27409838, 2016). "Collectively, our findings demonstrate a novel role for FOXC2 as a regulator of the G2/M transition and elucidate the reason for the observed sensitivity of CSC-enriched breast cancer cells to PLK1 inhibitor." (PMID 27064522, 2016). "Mechanistically, targeting mTOR appeared to mediate miR-100's function in sensitizing breast cancer cells to paclitaxel, but other mechanisms also seem to be involved, including targeting other molecules such as PLK1." (PMID 26744318, 2016). "We measured quantitative dose responses for 53 breast cancer cell lines to inhibitors of PLK1, CENPE and AURKB/C designated GSK462364 GSK923295 and GSK1070916, respectively." (PMID 27368372, 2016). "In this sense, PLK1 levels have been related to improved sensitivity to paclitaxel and trastuzumab when combined with siRNA targeting PLK1 in breast cancer cell lines in a synergistic way." (PMID 27409838, 2016). "To study the impact of Plk1 inhibition on the homing ability of ASCs toward injured or inflammatory sites, we performed an established attraction assay with two different breast cancer cell lines." (PMID 27713178, 2016). "We investigated the role of FBXW7 and their substrates MCL1 and PLK1 in regulating the apoptotic response to paclitaxel treatment in breast cancer cells and their expression in breast cancer tissues." (PMID 27409838, 2016). "Phospho-TCTP expression levels were reduced by treatment with BI 2536, a selective PLK1 inhibitor, confirming that TCTP is phosphorylated by PLK1 in mammary carcinoma cells." (PMID 25779659, 2015). "PLK1 is a crucial serin/treonin kinase in regulating cell proliferation, whose overexpression has been observed in many tumors, including breast cancer." (PMID 25779659, 2015). "Examination of Polo-like kinase 1 (PLK1) gene silencing effect of breast cancer cells indicated a specific gene knockdown in Her+-positive cells suggesting an increased apoptosis and reduced proliferation which leads to suppression of tumor growth." (PMID 24276320, 2013). "Expression levels of only two genes (MELK, PLK1) gave positive Beta coefficients with breast cancer recurrence and mortality, with HRs between 1.20 and 1.25." (PMID 23819905, 2013). "Recently, a similar strategy using a fusion of Her2 antibody and protamine loaded with Plk1 siRNAs was shown to suppress proliferation of Her2 positive breast cancer cells and primary human cancers in orthotropic breast cancer models." (PMID 23667320, 2013). "Blocking PLK1 had the greatest growth inhibition on breast cancer cells and TICs by about 80% to 90% after 72 hours." (PMID 22309939, 2012).
breast carcinoma (continued). "Numerous studies have now established that PLK1 is a prime target for drug development in proliferative diseases such as breast cancer." (PMID 22309939, 2012). "PLK1 was universally expressed in breast cancer cell lines, representing all of the breast cancer subtypes, and was positively correlated to CD44." (PMID 22309939, 2012). "Like its siRNA counterpart, PLK1 small-molecule inhibitor BI 2536 showed a significant growth-inhibitory effect on the cells of the seven different breast cancer cell lines under experimental conditions." (PMID 22309939, 2012). "Thirty one genes are overlapped in the PLK1-MCM complex-SKP2 subnets of breast cancer patient datasets (37 genes in total) and the one of NSCLC patient datasets (42 genes in total)." (PMID 22838965, 2012). "Analysis with Western blot confirmed that PLK1 is commonly expressed in all eight breast cancer cell lines tested." (PMID 22309939, 2012). "Expression of the interacting genes in the PLK1-MCM complex-SKP2 subnet of breast cancer patient datasets is positively correlated in ER positive samples and ER negative samples." (PMID 22838965, 2012). "We have previously found that cell cycle arrest of breast carcinoma cell lines at the G2/M boundary comprises repression of the gene for Plk1, PLK." (PMID 16887021, 2006). "Consistent with the G2/M phase accumulation of both cells lines, TSA-dependent Plk1 repression was seen, similar to what we have observed previously in a breast carcinoma cell line." (PMID 16887021, 2006). "Taken together, these data provide evidence that G2/M blockade by clinical-grade AukB or PLK1 inhibitors may be a viable clinical strategy in ER+ breast cancer cells, including certain CDK4/6i-resistant cancers." (PMID 40764324, 2025). "Up-regulation of PLK1 in some of the breast cancer subtypes may inhibit tumor development by interfering with cytokinesis and mitosis as well as one of the NIMA kinases NEK9, which is associated with tumor growth prevention, when upregulated." (PMID 40724805, 2025). "Leveraging bioinformatics tools and experimental validation, the research explores the interactions between C. urens components and key genes, including CDK1, CDC25A, and PLK1, which are crucial for cell cycle regulation and often dysregulated in breast cancer." (PMID 40081286, 2025). "The prognostic significance of PLK1 in breast cancer is subtype-dependent." (PMID 40092695, 2025). "AURKA and PLK1 are essential mitotic regulators that promote the G2/M transition and are often overexpressed in aggressive breast cancers, while CDC25C facilitates CDK1 activation and has been associated with unchecked cell cycle progression in high-grade tumors." (PMID 41017855, 2025). "Therefore, we generated dose-response curves for four of these inhibitory compounds in multiple PLK1-overexpressing breast cancer cell lines to determine their half maximal inhibitory concentration (IC50)." (PMID 40347943, 2025). "Similarly, while Plk1 is overexpressed in breast cancer, it can also induce chromosomal instability, interfere with mitosis, and suppress tumors." (PMID 41357585, 2025). "PLK1 or AukB inhibitors that block G2/M phase may have a clinical impact on CDK4/6i-resistant ER+ breast cancers." (PMID 40764324, 2025). "In the present study the treatmnet of MCF7 cell treated with the CU (200–500 μL) fraction for 24 h and significantly down regulation of the CDK1, CDC25A and PLK1 which is involved in cell cycle, and responsible for cell cycle arrest in tumour cells of breast cancer." (PMID 40081286, 2025). "In addition, PLK1 was positively correlated with myeloid-derived suppressor cells (MDSCs) and regulatory T cells in breast cancer and node-predominant Hodgkin’s lymphoma." (PMID 40612941, 2025).
breast carcinoma (continued). "Likewise, a reduction in PLK1 activity increases the sensitivity of breast cancer to radiation therapy, whereas enhanced expression of PLK1 contributes to the development and advancement of liver tumors." (PMID 38953023, 2024). "We further explored the role of PLK1 in breast cancer and found that it could effectively distinguish normal individuals from breast cancer patients across different subtypes and pathological stages." (PMID 39596658, 2024). "Notably, PLK1 was found to be upregulated in bone metastasis-derived patient-derived xenograft (PDX) models from HR+ breast cancer patients who progressed on ET compared to their matched primary tumors." (PMID 39409880, 2024). "Notably, transcriptomic analysis predicted the mechanistic involvement of PLK1 in LAS-suppressed breast cancer progression." (PMID 38495493, 2024). "We found that proteins expression of CDC25C and p-AKT(T308) were significantly decreased in SK-BR-3 and MDA-MB-231 cells treated with LAS (1,3 μM) compared to that of controls, suggesting that LAS inhibited the phosphorylation of CDC25C and AKT via regulating PLK1 pathway in breast cancer cells." (PMID 38495493, 2024). "Additionally, we observed that PLK1 was overexpressed in breast cancer tissues, peripheral blood, and cell lines, highlighting its diagnostic value." (PMID 39596658, 2024). "Ultimately, we confirmed that LAS inhibit breast cancer growth via inhibiting PLK1 pathway in vivo." (PMID 38495493, 2024). "Previous investigations provided a compelling rationale for targeting PLK1 in HR+ breast cancer." (PMID 39409880, 2024). "Moreover, the expression of PLK1 was also upregulated in breast cancer cell lines compared to normal breast epithelial cells." (PMID 39524172, 2024). "Taken together, these data suggest that LAS may induce G2/M phase arrest of breast cancer cells by regulating PLK1 expression." (PMID 38495493, 2024). "Since SAMD5 negatively correlates with PLK1, the dynamic effects of SAMD5 and PLK1 on breast cancer cells were explored to investigate whether PLK1 mediates SAMD5 functions in breast cancer." (PMID 39524172, 2024). "Blocking the CXCL12/CXCR4 pathway may suppress the growth of breast cancer cells by reducing the expression of proteins that facilitate the G2-M phase transition (PLK1, Myt1, and cyclin B1), and then disrupting mitotic processes." (PMID 39703847, 2024). "The expression and functions of PLK1 in breast cancer cells were investigated." (PMID 39524172, 2024). "• First selective PLK1 inhibitor.• Further reduces the invasion and spread of breast cancer." (PMID 38606093, 2024). "RGCC promotes breast cancer lung metastasis by regulating the kinase activity of PLK1." (PMID 38102722, 2023). "In addition to PLK1, PGCCs up-regulated CDC20 and CCNB1, which are associated with aneuploidy/polyploidy, adverse clinical outcomes of breast cancer patients, and resistance to adjuvant therapy." (PMID 38129519, 2023). "It was reported that the down-regulation of PLK1 induced apoptosis, premature senescence, and elevation drug sensitivity of breast cancer cells and decreased the viability of cancer cells in endothelial cells, cell cycle arrest, and apoptosis of cutaneous T-cell lymphomas." (PMID 36673375, 2023). "This strongly suggests that RGCC/PLK1 may mediate lung metastasis of breast cancer through metabolic reprogramming via regulating AMPKα2." (PMID 38102722, 2023). "In addition, PLK1 is a potential drug target on account of its high expression in advanced breast cancer stages." (PMID 38186570, 2023).